FAM90A18 (family with sequence similarity 90 member A18)
Synonyms: FAM90A18P; FAM90A19P
Tractability: No criterion of Open Targets' tractability assessment is met for any kind of drug.
Gene: Protein-coding gene on chromosome 8 (7,723,091 to 7,726,101, forward strand). Ensembl gene ENSG00000285913.
Subcellular location (Human Protein Atlas): Nucleoplasm; Nucleoli
Homologues: Orthologues: mouse Fam90a1b (28% identical), mouse Fam90a1a (27% identical), rat Fam90a1l1 (26% identical). Paralogues in human: FAM90A19 (100% identical), FAM90A9 (99% identical), FAM90A16 (99% identical), FAM90A17 (99% identical), FAM90A8 (98% identical), FAM90A10 (98% identical), FAM90A15 (98% identical), FAM90A13 (97% identical), FAM90A14 (97% identical), FAM90A23 (97% identical), FAM90A3 (97% identical), FAM90A5 (97% identical), and 9 more.